HLA-P (major histocompatibility complex, class I, P (pseudogene))
Synonyms: dJ377H14.3; formerly C6orf101; HLA-90
Gene: Unprocessed pseudogene on chromosome 6 (29,800,415 to 29,802,425, forward strand). Ensembl gene ENSG00000261548.
Diseases named in the same sentence as HLA-P in open-access papers:
HLA-P is named in the same sentence as 3 diseases in open-access papers, as found by Europe PMC text mining. Sharing a sentence is not in itself a finding about the gene and the disease. The quoted sentences say what the papers report.
melanoma (1 paper, 2020). A malignant, usually aggressive tumor composed of atypical, neoplastic melanocytes. "To experimentally validate the NewAnce computational pipeline, we investigated a selection of NewAnce-identified HLAp from a melanoma sample (0D5P) with targeted MS-based analyses." (PMID 32157095, 2020).
cancer (1 paper, 2017). A tumor composed of atypical neoplastic, often pleomorphic cells that invade other tissues. "In cancer, HLAp derived from processing and presentation of cancer-specific proteins serve as the leading targets for T-cell recognition." (PMID 29104575, 2017). "The adaptive immune system has the capacity to elicit anti-cancer CD4+ and CD8+ T-cell responses, which are triggered by the presentation of cancer-derived antigens as human leukocyte antigen-binding peptides (HLAp) and their recognition by cognate T-cell receptors." (PMID 29104575, 2017).
tumor (1 paper, 2024). "The gene-modification of mouse tumor cell lines to stably cell-surface express target HLAp proved to be challenging." (PMID 39794936, 2024). "In order to perform in vivo studies, we next needed to gene-modify murine tumor cells to stably cell-surface express the target HLAp complex." (PMID 39794936, 2024). "We observed some reactivity of supraphysiological affinity wtc51m-T cells against B16-A2Kb:NY cells, possibly due to higher levels of the HLAp SCT than may be naturally present on tumor cells (ie, A375, Me275)." (PMID 39794936, 2024).